IL17D (interleukin 17D)
Diseases named in the same sentence as IL17D in open-access papers (continued):
Sharing a sentence is not in itself a finding about the gene and the disease.
inflammatory skin disease (3 papers, 2022 to 2026). Inflammatory skin disorders covers a broad category that includes many conditions ranging in severity, from mild itching to grave medical health complications These disorders are common in people of all ages and races. "Similarly, in inflammatory skin diseases, IL-17D regulates keratinocyte-mediated inflammatory responses through the CD93‒p38 MAPK‒protein kinase B (AKT)-Smad2/3 signaling axis." (PMID 40536951, 2026).
melanoma (3 papers, 2017 to 2022). A malignant, usually aggressive tumor composed of atypical, neoplastic melanocytes. "NRF2 has been purported to induce IL-17D to recruit natural killer cells, mediating tumor regression in a murine melanoma model." (PMID 36359002, 2022). "We found that Il17d−/− mice were resistant to tumor growth upon B16 OVA melanoma and E.G7 OVA lymphoma challenge." (PMID 31244826, 2019). "Interestingly, the expression of IL-17 (only IL-17D isoform) is clearly downregulated in BCG-injected melanoma lesions." (PMID 28424760, 2017).
rheumatoid nodule (3 papers, 2018 to 2022). "IL-17 family members are involved in RA pathogenesis and IL17D is expressed in rheumatoid nodules." (PMID 35820911, 2022). "IL-17D RNA has been detected in rheumatoid nodules, where IL-17A is absent, but not in peripheral blood mononuclear cells or in synovial fluid from patients with rheumatoid arthritis." (PMID 33244315, 2020). "IL-17D levels have been reported increased in rheumatoid nodules." (PMID 30127781, 2018).
dementia (2 papers, 2023 to 2026). Loss of intellectual abilities interfering with an individual's social and occupational functions. "Our findings highlight the upregulation of several functionally immune-related proteins in dementia, such as IL17D, IL17C, IL17RB, and IL1B, among which IL17D also showed a strong negative correlation with cognitive performance." (PMID 37175824, 2023). "Interestingly, six proteins (NEFL, WNT9A, IL17D, IGFBP2, KLK4, and PGF) were repeatedly selected in both diagnostic models that classified dementia from both cognitively normal controls and MCI." (PMID 37175824, 2023). "Notably, NEFL, WNT9A, IL17D, IGFBP2, KLK4, and PGF proteins were included in both models that differentiated dementia from either cognitively normal controls or MCI." (PMID 37175824, 2023).
leprosy (2 papers, 2013 to 2016). Leprosy is a chronic infectious disease affecting primarily the skin and peripheral nervous system. "That the IL-17 release was also influenced by the leprosy spectrum was indicated by BT patients who showed significant increase in expression of IL-17 isoforms: IL-17A (p<0.0002), IL-17C (p<0.003), IL-17D (p<0.003) and IL-17F (p<0.0001) as compared to the multibacillary LL patients." (PMID 23936569, 2013).
Listeria infection (2 papers, 2019 to 2022). "In a RAG-deficient background, IL-17D-deficient mice showed an increase in both the number and activated status of DCs compared with that in WT mice after listeria infection." (PMID 31244826, 2019). "While IL-17D was redundant in several acute and chronic inflammation models, IL-17D-deficient mice were resistant to Listeria infection with an increased cytotoxic CD8 T cell response compared to WT mice." (PMID 31244826, 2019). "Since IL-17D-deficient mice were resistant to Listeria infection, we evaluated pathogen burden upon other infection such as influenza virus and provided unexpected insights into the role of IL-17D in compromising the host defensive function." (PMID 31244826, 2019). "CD4 depletion, however, did not reverse the bacterial burden, indicating that IL-17D exerts a pathogenic function during Listeria infection by repressing CD8 T cell activity." (PMID 31244826, 2019). "To substantiate our findings on reduced pathogen burden in IL-17D-deficient mice, we examined cellular mediators that promote bacterial clearance in the absence of IL-17D and found that CD8 T cell activity was enhanced in IL-17D-deficient mice in Listeria infection." (PMID 31244826, 2019). "Our results using bone marrow chimera indicated that non-hematopoietic compartments of IL-17D contributed to pathogenicity during Listeria infection and lymphoma challenge." (PMID 31244826, 2019). "Here, we showed that the lack of IL-17D expression confers protection against Listeria infection." (PMID 31244826, 2019). "We observed that IL-17D expression was reduced in the infected liver tissues, CD45 negative cells and hepatocytes after Listeria infection." (PMID 31244826, 2019).
Sepsis (2 papers, 2022 to 2024). Sepsis is defined as life-threatening organ dysfunction caused by a dysregulated host response to infection. "The levels of IL-17D were significantly elevated in patients with sepsis." (PMID 35071607, 2022). "IL-17D inhibits the phagocytosis of macrophages by inhibiting activation of the nuclear factor- (NF-) κB signaling pathway and ultimately aggravates the symptoms in sepsis patients." (PMID 35071607, 2022). "However, reports of sepsis and listeria infections have also revealed the harmful side of IL-17D." (PMID 35071607, 2022). "Previous studies had identified several biomarkers such as oncostatin M (OSM), apoptosis inhibitor of the macrophage (AIM/CD5L), interleukin-26 (IL-26), interleukin-17D (IL-17D), interleukin-37 (IL-37), and growth differentiation factor-15 (GDF-15) as potential predictors of sepsis prognosis." (PMID 38318247, 2024).
atherosclerosis (1 paper, 2022). A disease characterized by the build-up of fatty material and calcium deposition in the arterial wall resulting in partial or complete occlusion of the arterial lumen. "The transcript levels of other two IL-17 subtypes, IL-17B and IL-17D, are reduced in psoriatic lesions, but the effects of IL-17B and IL-17D in atherosclerosis are unknown." (PMID 35514987, 2022).
atrial fibrillation (1 paper, 2024). A disorder characterized by an electrocardiographic finding of a supraventricular arrhythmia characterized by the replacement of consistent P waves by rapid oscillations or fibrillatory waves that vary in size, shape and timing and are accompanied by an irregular ventricular response. "Clinical data indicate that in a cohort of 2,032 heart failure patients, higher plasma IL-17D concentrations are significantly associated with atrial fibrillation, increased levels of plasma N-terminal brain natriuretic peptide precursor, and poorer prognosis." (PMID 39502194, 2024). "Moreover, multivariate Cox regression analysis revealed that elevated plasma IL-17D levels were associated with significantly increased risks of combined outcomes including atrial fibrillation, heart failure hospitalization, and all-cause mortality." (PMID 39502194, 2024).
Autoimmunity (1 paper, 2022). The occurrence of an immune reaction against the organism's own cells or tissues. "The up- or down-regulation of IL-17 genes (IL-17A, IL-17B, IL-17D, and IL-17F) resulted in decreased expression of many cytokines and chemokines, which are associated with autoimmunity and immune cell functions." (PMID 35466218, 2022).
cervical tumors (1 paper, 2022). "We found that downregulated genes in PR patient, such as IL17D, MDK and GNRH1, which are known for their role in the innate immune system, are unfavorable prognostic factors highly expressed in primary cervical tumors and across cancers." (PMID 36171464, 2022).
cytomegalovirus infection (1 paper, 2019). A herpesvirus infection caused by Cytomegalovirus. "On the other hand, vaccina virus or mouse cytomegalovirus infection induced IL-17D expression in primary fibroblasts." (PMID 31244826, 2019). "In addition to non-immune cells, peritoneal cavity cells, including mostly macrophages and B cells, upon mouse cytomegalovirus infection expressed an increased level of IL-17D." (PMID 31244826, 2019).
dental caries (1 paper, 2021). The decay of a tooth, in which it becomes softened, discolored, and/or porous. "On the other hand, dental caries are significantly correlated to SNPs in IL-17D." (PMID 34539639, 2021).
depression (1 paper, 2020). "IL-17, a pro-inflammatory cytokine, is a member of the cytokine family comprising IL-17A, IL-17B, IL-17C, IL-17D, IL-17E (IL-25) and IL-17F and it was found before, to be elevated in the serum of patients suffering from depression." (PMID 33322667, 2020).
experimental autoimmune encephalomyelitis (1 paper, 2019). An autoimmune demyelinating disease of the central nervous system that is produced experimentally in animals by the injection of homogenized brain or spinal cord in Freund's adjuvant. "IL-17D was dispensable in several inflammation settings, lipopolysaccharide (LPS)-induced endotoxin shock, experimental autoimmune encephalomyelitis (EAE), and allergic lung inflammation." (PMID 31244826, 2019).
fungal infections (1 paper, 2024). "The IL‐17 family of cytokines consists of six groups: IL‐17A, IL‐17B, IL‐17C, IL‐17D, IL‐17E and IL17‐F, which are involved in the development of autoimmunity, inflammation, tumours, host defences against bacterial and fungal infections, and mucosal host defence mechanisms." (PMID 38363001, 2024).
pulmonary fibrosis (1 paper, 2022). Chronic progressive interstitial lung disorder characterized by the replacement of the lung tissue by connective tissue, leading to progressive dyspnea, respiratory failure, or right heart failure. "Knowledge of IL-17D in the regulation of pulmonary fibrosis remains limited, and further investigations are needed to understand the relationship between IL-17D-induced inflammatory response and pulmonary fibrosis development." (PMID 35550651, 2022).
respiratory infections (1 paper, 2025). "The IL17D gene is involved in the inflammatory response to respiratory infections." (PMID 40565522, 2025).
Salmonella Infections (1 paper, 2021). Infections with bacteria of the genus SALMONELLA. "Predictably, 2W-Salmonella infection induced T cell-intrinsic expression of genes involved in type 1 and type 17 immune responses, including Tbx21 (Tbet), Rorc (RORγt), Il17d/f and Il22." (PMID 34237106, 2021).
staphylococcal infection (1 paper, 2024). An infection caused by Staphylococcus. "The role of IL-13RA2 and IL-17D in bacterial pathogenesis has not been well delineated, but the higher levels of these cytokines in staphylococcal infections suggest that the immune mediators are dependent upon the type of infecting microorganism." (PMID 39770689, 2024).
tendinopathy (1 paper, 2025). "In addition, here, we demonstrate the differential expression of IL17A in contrast to the other IL-17 family members, IL17B, IL17C, IL17D and IL17E in early-stage tendinopathy compared with late-stage tendinopathy and healthy tendon." (PMID 39988349, 2025).
type 2 diabetes (1 paper, 2024). "IL-17D is associated with incident type 2 diabetes and progression from normoglycemia to type 2 diabetes." (PMID 39696496, 2024).
tumor (26 papers, 2014 to 2026). "These genes are associated with macrophage recruitment and polarization, accompanied by robust phosphorylation of p38 MAPK, indicating that IL-17D activates the p38 MAPK signaling pathway to promote tumor-associated macrophage infiltration." (PMID 40536951, 2026). "Mice deficient in IL-17D not only showed stronger tumor susceptibility but also showed more severe infection symptoms after infection with vaccinia virus (VV) and murine cytomegalovirus (MCMV), such as longer scar length and lower body weight." (PMID 35071607, 2022). "Using flow cytometry, we found that IL-17D overexpression enhances the recruitment of tumor-associated macrophages to the tumor microenvironment." (PMID 35939336, 2022). "Mechanically, IL-17D induced tumor associated macrophages (TAMs) infiltration via the p38 MAPK pathway." (PMID 35939336, 2022). "One of the most differentially expressed genes was IL17D encoding interleukin 17D (IL-17D), with a significantly increased expression in unedited tumor cells." (PMID 33322371, 2020). "Additionally, activating Nrf2 to cause IL-17D in pre-existing tumors resulted in tumor regression mediated by natural killer cells." (PMID 37946175, 2023). "Thus far, IL-17D has been implicated in stress response, intestinal homeostasis as well as anti-viral and anti-tumor responses." (PMID 36140808, 2022). "A higher IL-17D staining intensity was associated with the tumor stage of NSCLC." (PMID 35939336, 2022). "Owing to the different growth trends in vitro and in vivo, the major function of IL-17D in tumor growth might be associated with the tumor microenvironment (TME)." (PMID 35939336, 2022). "While research on IL-17D is still limited, existing studies suggest that IL-17D is involved in tumor progression and anti-infection responses." (PMID 40536951, 2026). "IL-17D overexpression increases macrophage polarization and infiltration, promoting tumor growth and progression." (PMID 40536951, 2026). "CD93 has recently been recognized as a key receptor that interacts with IL-17D, and its involvement in regulating angiogenesis, inflammation, and tumor progression has been well documented." (PMID 40536951, 2026). "Adaptive immune mediators included IL‐12, Granzyme B, CD40, PD‐L1, and IL‐17D, suggesting broad effects of alpha 1‐oleate treatment on the tumor tissues." (PMID 38553868, 2024). "Nrf2 can also aid anti-tumor immunity by inducing immune-dependent cascades such as IL-17D-dependent NK (natural killer) cell recruitment early in carcinogenesis before the pro-tumor action of Nrf2 manifests." (PMID 36747120, 2023). "We found that subcutaneous tumor growth of IL-17D–expressing LLC1 cells was faster than that of vector-transduced cells." (PMID 35939336, 2022). "Recent report indicated that Il17d−/− mice were resistant to tumor growth upon B16 OVA melanoma and E.G7 OVA lymphoma challenge through enhancing CD8 T cell activity." (PMID 35939336, 2022). "IL-17D overexpression significantly promoted tumor growth in subcutaneous xenograft mouse models but only slightly affected cell proliferation in vitro." (PMID 35939336, 2022). "The tumor weight of IL-17D–expressing cells was also significantly higher than that of the vector-transduced cells." (PMID 35939336, 2022). "IL-17D–induced tumor growth and infiltration of TAMs were significantly inhibited by the IL-17D antibody." (PMID 35939336, 2022). "We found that the percentage of F4/80+ CD11b+ TAMs among CD45+ tumor-infiltrating leukocytes (TILs) was significantly increased in IL17D–expressing tumors." (PMID 35939336, 2022). "The role of IL-17D towards tumor purity was the same as IL-17B, embodied in BRCA, HNSC, PAAD, SARC, TGCT, and UVM." (PMID 36159856, 2022). "In this study, IL-17D overexpression in a subcutaneous tumor model significantly inhibited CD8+ T cell infiltration." (PMID 35939336, 2022).
tumor (continued). "Expression of IL-17D has been found in fibroblasts, skeletal muscle, brain, adipose tissue, tumor cell lines, heart, lung, pancreas, as well as colon epithelial cells." (PMID 36140808, 2022). "IL-17D stimulates endothelial cells to express MCP-1 for the recruitment of NK cells to elicit an effective anti-tumor or anti-viral effect." (PMID 36140808, 2022). "Gene expression analyses on human samples will define potential correlates between tumor immune infiltrate and expression of both IL-17A and IL-17D." (PMID 33244315, 2020). "As an example, Tert-butylhydroquinone (tBHQ) has been tested in preclinical models of B16 melanoma, human Burkitt’s lymphoma, and in the MCA-induced sarcoma, where activated Nrf2 and IL-17D production, resulting in delayed tumor progression." (PMID 33244315, 2020). "Overexpression of IL-17D in edited tumor cells induced tumor rejection by stimulating CCL2 production from tumor endothelial cells, leading to an increase in the recruitment of NK cells." (PMID 33322371, 2020). "Activated NRF2 in cancer cells can induce IL-17D expression that recruits NK cells, resulting in increased anti-tumor immunity and NK-dependent tumor regression." (PMID 32640524, 2020). "A recent report indicated that it is highly secreted by fibrosarcoma tumor cells; in addition, ectopic expression of IL-17D in tumor cells recruits natural killer cells via the CCL2 production of endothelial cells." (PMID 31244826, 2019). "Inducing IL-17D using Nrf2 agonists boost innate immunity and NK recruitment leading to tumor-regression." (PMID 31057536, 2019). "IL-17D expression was also decreased in certain high-grade and metastatic human tumors, suggesting that it can be targeted for tumor immune therapy." (PMID 29548303, 2018). "IL-17D expression was also lowered in certain high-grade and metastatic human tumors, suggesting that it can be targeted for tumor immune therapy." (PMID 25590298, 2015). "In addition, IL-17D can stimulate tumor endothelial cells to express monocyte chemotactic protein 1 (MCP-1) and recruit NK cells and macrophages into the tumor microenvironment to play an antitumor role." (PMID 35071607, 2022). "These suggest that IL-17D may exhibits a variety of functions in different tumor types and stages of tumor development." (PMID 35939336, 2022). "IL-17A, IL-17B, IL-17C, as well as IL-17F have been shown to promote tumor development, whereas IL-17D and IL-17E play anti-cancer roles in a context-dependent manner by activating the Nrf2 stress surveillance pathway, recruiting innate immune cells, and activating leukocytes." (PMID 36140808, 2022). "Additionally, oxidative stress, due to tumor development or viral infection, induces transcription factor Nrf2 to promote IL-17D expression." (PMID 36140808, 2022). "Finally, Nrf2, a cellular checkpoint of xenobiotic and oxidative stress is an interesting molecule, as it delays tumor growth by stimulating IL-17D production in tumor cells, which recruits NK cells within the tumor." (PMID 33244315, 2020). "However, NRF2 activation in tumor cells or virally infected cells induces IL-17D and thereby potentiating anti-tumor immunity and antiviral immunity against vaccina virus (VV) and mouse cytomegalovirus (MCMV)." (PMID 32640524, 2020). "While IL-17D and IL-17E appear to exert preponderant tumor-protective activities, IL-17B, IL-17C, and IL-17F are tumor promoting, either through a direct effect on tumor cells, or by modulating the tumor microenvironment." (PMID 33244315, 2020). "Since CD8 T cells are a key mediator of anti-tumor immunity, we examined whether Il17d−/− mice exhibited enhanced CD8 T cell activity upon tumor challenge." (PMID 31244826, 2019). "In addition, Nrf2 upregulation, regulates early anti-cancer immune responses and induces the cytokine interleukin-17D (IL-17D), that is overexpressed in highly immunogenic tumor cells and play an important role in immune rejection mediated by NK cells." (PMID 31057536, 2019).